IL17A (interleukin 17A)
Diseases named in the same sentence as IL17A in open-access papers (continued):
Sharing a sentence is not in itself a finding about the gene and the disease.
tumor (continued). "They focus functional studies on IL-17A–producing γδ T cell subsets, showing that the co-inhibitory molecules, PD-1 and TIM-3, regulate cell expansion in tumor-bearing mice, which counteracts anti–PD-1 or anti–TIM-3 immunotherapy." (PMID 36480166, 2023). "In this context, IL-17 A cytokine is the mostly known as pro-angiogenic mediator now a days, due to its involvement in inflammatory process and TNF-alpha secretion in tumor microenvironment." (PMID 37563607, 2023). "IL-17A expression triggered by TLR4 signaling in hepatocytes was attenuated after FGF21 restoration, and anti-IL17 treatment reduced HCC tumor size." (PMID 37175993, 2023). "We performed immunohistochemical staining of tumours and showed that the proportion of CD8 + T cells was significantly increased in the mice in the IL-17A-treated group." (PMID 37211606, 2023). "In agreement with these functions, our MPM AFs showed increased expression of IL-6, IL-17A, PDGFs, various FGFs and IGF-1, all molecules reported to improve the survival and chemoresistance of tumour cells through their cross-talk with CAFs." (PMID 37938546, 2023). "Recent investigation of IL-17A directly on T cells by using Il17a−/− mice reported that IL-17A can promote terminal exhaustion of CD8+ T cells and tumor progression." (PMID 37605139, 2023). "The assay revealed that IL-17A induced a mild increase in H2O2 and superoxide anion production by tumor cells." (PMID 37978543, 2023). "In GC, TANs secrete IL‐17a through the ERK pathway to promote the progression and metastasis of tumor cells." (PMID 35833662, 2023). "Our data also suggested a substantial correlation between IL-17A and CD8+ T cell infiltration in LLC tumors and indicated a probable mechanism of the indirect anti-tumor effect of Type 17 T cells." (PMID 35459193, 2022). "Our in vitro data also showed that when the microbiota, cancer cells, and immune cells were present simultaneously, the abundance of M2-TAMs, the level of IL-17A secreted by γδ T cells, and the phosphorylation level of STAT3 in tumor cells peaked." (PMID 36000726, 2022). "It has also been reported that neutrophils interact with tumor cells by using the same molecular machinery that induces EMT such as TGF-β, IL-8, CCl2, TNF-α, and IL-17a." (PMID 36091114, 2022). "Beside interleukin-6 (IL-6), the high level of which is observed in patients with a high mortality rate, other cytokines IL-17A, IL-22, and transforming growth factor -β (TGF-β) are expressed at the tumor level." (PMID 36361758, 2022). "In the current study, we found that Vγ1 γδ T cells are the major IL-17A-producing cells in the TME, which differs from prior reports that Vγ4- and Vγ6-restricted cells constitute the dominant γδT17 cell population in tumours." (PMID 35017553, 2022). "PMN-MDSC actively communicate with cancer cells through inflammatory mediators and growth factors such as IL8, IL17a, CCL2, TNFα, BV8, VEGFα, and TGFβ plays important roles in various aspects of tumor cell dissemination, invasion, and angiogenesis." (PMID 35504900, 2022). "An ELISA experiment also verified the increase of the secreted IFN-γ protein in the tumor tissues of mice treated with 8-074 in LLC model mice, suggesting that the expressions of IL-17A and IFN-γ are positively correlated." (PMID 35459193, 2022). "At the same time, IL-17A induces the production of CXCL-1 and CXCL-5, leading to the recruitment of the expanded myeloid cells into the tumor where they help to establish a tumor promoting microenvironment." (PMID 36611932, 2022). "Further studies demonstrated that CQF significantly reduced IL-17A levels, which in turn inhibited NF-κB/IL-6/STAT3 signaling cascade, suppressed MMP9 expression and promoted tumor cell apoptosis." (PMID 35991881, 2022). "Among which, the expressions of anti-tumor cytokines including IL-2, IL-15 IL-17A, IFN-γ and TNF-α were up-regulated, while tumor-promoting cytokines including IL-4 and IL-10 were down-regulated in HER2.28ζ/PD-L1.BB CAR-T cells." (PMID 36402752, 2022).
tumor (continued). "On the other hand, Th17 CD4, producing interleukin-17A (IL-17A) present in CRC, facilitates tumor progression in human and in experimental models." (PMID 36361758, 2022). "To evaluate the correlation between IL17A and HNSCC, we used the TCGA database to identify differences in the levels of IL17A mRNA in normal and tumor tissues." (PMID 35902909, 2022). "In summary, IL-17A induced CTSK expression to disrupt E-cadherin/β-catenin complex, released β-catenin, and enhanced EMT and tumor cell invasion." (PMID 36138018, 2022). "In our own studies, deletion of IL-17A in a KM-LUAD mouse model reduced tumor burden, inflammation, and pro-tumor myeloid cell recruitment and infiltration." (PMID 35406557, 2022). "Tumor-prone mice co-colonized with Escherichia coli and ETBF show increased IL-17A level in the colon and DNA damage in colonic epithelia, with faster tumor onset and greater mortality, compared to mice with either bacterial strain alone." (PMID 35967333, 2022). "To further examine the role of IL-17A in tumour regression following BTNL2 blockade, we neutralized IL-17A in tumour-bearing mice and found that this completely abolished the anti-tumour effect of BTNL2 blockade." (PMID 35017553, 2022). "We then analyzed the public database of Tumor IMmune Estimation Resource (TIMER2.0) and found that IL-17A was positively correlated with the number of activated NK and CD8+ T cell infiltration in LUAD and LUSC." (PMID 35523765, 2022). "Th17 cells secrete IL-17A, which stimulates vascular endothelial growth factor (VEGF), resulting in tumor angiogenesis." (PMID 35619903, 2022). "IL-17A promotes CRC cell proliferation, tumor growth, and angiogenesis resulting from VEGF production in CRC." (PMID 36140808, 2022). "Administration of neutralizing antibodies for PN, or WNT3A, or IL17A, or CD44v6 increased the efficacy of FOLFOX-chemotherapy on reducing tumor growth." (PMID 35982950, 2022). "On a functional level, in vivo studies in colitis-associated cancer were able to confirm that TGFβ relevantly contributed to the intratumoral accumulation of IL-17A+ IL-22+ CD4+ T cells and thereby obviously triggered IL-22-dependent tumor-promoting effects." (PMID 36428508, 2022). "Interleukin-17A is a proinflammatory cytokine that is produced by TH17 cells, and plays a dual role in tumor progression, infectious diseases, and autoimmune disorders." (PMID 36098359, 2022). "In this phase, N1 TANs exert cytolytic functions primarily through ROS production and stimulate tumor specific T cells by antigen presentation and pro-inflammatory cytokine production such as IL-1β, IL-6, TNF-α, or IL-17A." (PMID 34168563, 2021). "The median number of IL-17A+ cells isolated from the tumor tissue was significantly lower with respect to IL-17A-expressing cells in the PBMC (5.6% ± 3.2) and to IL-17A+ TILs isolated from BCC biopsies (19.5% ± 7)." (PMID 34944746, 2021). "RFX1 downregulates such pro-tumor factors like Toll-like receptor 4 (TLR4), Interleukin 17A (IL17A), interleukin 5 receptor subunit alpha (IL5RA), and helps in cancer mitigation while being anti-inflammatory." (PMID 33964962, 2021). "To validate the signal transmission in MSS CRC tissues, we analyzed the correlations between IL-17A, NRF1, miR-15b-5p, and PD-L1 expression in MSS CRC tumor specimens obtained from 160 patients." (PMID 33462141, 2021). "We then detected the IL-17A+cells in their tumor tissues and found that the counts of IL-17A+cells in two patients were less than 10/HPF, including one patient with PR and one patient with stable disease (SD, tumor reduction of 16% relative to baseline)." (PMID 33462141, 2021). "These conventional chemotherapies activate CAFs to create a chemoresistant niche through IL-17A, which is a CSC maintenance factor that promotes self­renewal and tumor growth." (PMID 33953165, 2021).
tumor (continued). "Here, our data show a higher accumulation of tumor-infiltrating CD39+γδ Tregs in RSCRC than paired normal tissue and LSCRC, along with increased production of IL-17A and adenosine, as well as upregulation of Tim-3." (PMID 34283812, 2021). "Given its key role in promoting expression of IL-8 by various cell types, including tumor cells that promote influx of neutrophils/MDSCs into the TME, IL-17A also represents a prominent target for the control of neutrophilic inflammation." (PMID 34168563, 2021). "attempted to introduce new therapies based on Th17 lymphocytes which produce IL-17A, IL-17F, IL-21, IL-22, IL-26, IL-6, TNF-α and suppress tumour progression through enhanced antitumor immunity in OC." (PMID 34621670, 2021). "These cells produce various tumor-promoting cytokines, including TNF-α, IL10, and IL17A, and also the less well-studied cytokines such as IL21 and IL26." (PMID 31948053, 2020). "Additionally, IL-17 but not IL-23 expression was associated with recurrence/mortality, suggesting that the enrichment of IL-17A in tumor microenvironment may be related to aggressiveness in thyroid cancer." (PMID 32139737, 2020). "IL-17A, predominantly secreted from Th17 cells, inhibited STAT3-dependent CXCR3 expression on CD8+ T cells, leading to decreased CD8+ T cell migration to tumor tissues." (PMID 32503584, 2020). "Therefore, its increase in 4T1 tumor tissue, lymph nodes or iTh17 cells (current work) from young mice was predictable and may have contributed to the observed enhanced differentiation of iTh17 cells and the production of IL-17A in young mice." (PMID 32257539, 2020). "Specifically, tumor tissue supernatants from WT and GCSFR−/− mice tumors were assessed for the production of IFNγ, IL-10, IL-17A, and IL-4, which are considered general markers of Th1, Tregs, Th17, and Th2 cells, respectively." (PMID 33042110, 2020). "Next, we assessed the ability of lamina propria T cells from unaffected tissue and tumor tissue to produce some of the cytokines important in tumor immunity (IFN-γ, IL-2, IL-17A, and TNF)." (PMID 32185408, 2020). "Tumour-infiltrating CD73+γδ1 T cells express high levels of IL-4, IL-17A, IL-10, GM-CSF and TGF-β, and exert immunosuppressive functions mainly via the adenosine-mediated pathway." (PMID 32345959, 2020). "The aim of this study is to investigate the role of IL-17A in PTC with coexistent HT and evaluate the changes in tumor antigenicity." (PMID 31159823, 2019). "Meanwhile, the expression of IL‐17A in tumour specimen from patients with GBM had the parallel result to the protein and mRNA levels of IL‐17A." (PMID 30353649, 2019). "Our findings from in vitro functional studies and from transcriptomic analyses of tumor tissues and CRC-isolated Tregs also indicate an implication of the IL-33/ST2 axis in the regulation of IL-17A expression by FOXP3+ Tregs and FOXP3− CD4+ T cells." (PMID 31165767, 2019). "Ablation or blocking of IL-6 signaling resulted in reduced tumor growth in absence or presence of COPD-like airway inflammation and in mice constitutively expressing IL-17A in the lung epithelium." (PMID 31316109, 2019). "It has been observed that TANs actively communicate with tumor cells through growth factors or inflammatory cytokines such as TNFα, CCL2, IL-8, and IL-17a, which can promote tumorigenesis and progression." (PMID 30616627, 2019). "Remarkably, the percentage of IL‐17A+ cells was inversely correlated with the E‐cadherin level and positively related to the N‐cadherin level in both PVTT and primary tumour tissues." (PMID 29689643, 2018). "We detected the percentage of IL‐17A+ cells in 30 cases of PVTT and matched primary tumour tissues collected from patients with HCC who underwent surgical resection at EHBH." (PMID 29689643, 2018).
tumor (continued). "Neoadjuvant chemotherapy seemed to result in a relocation of Th1-committed CD4+ T cells from blood, presumably to the tumour, indicated by shifts in the methylation patterns, whereas no such shifts were seen for lineages corresponding to IL13, IL17A and FOXP3." (PMID 30075815, 2018). "For instance, inhibiting IL-17A at tumor sites significantly suppresses CD31, MMP9, and VEGF expression in the tumor, while activating its receptor (IL-17RA) promotes early tumor development." (PMID 29983876, 2018). "Recent evidence reports that injection of synthetic antitumor miRNAs successfully inhibits tumor metastasis in animal models, which sheds light on the exploitation of miR-23b based therapies to treat metastatic TSCC with IL-17A upregulation." (PMID 28035060, 2017). "We isolated IL-17A-producing Foxp3neg, IL-17A-producing Foxp3+ and IL-17Aneg Foxp3-expressing CD4+ T cells and injected the Th17 and Treg subsets in Cd45.1 tumour-bearing mice on days 5, 12 and 19 (n=4 per group)." (PMID 28290453, 2017). "Our IHC results showed that the expression of the intracellular cytokine IL-17A was lower, whereas that of IFN-γ was higher in tumor tissues compared with in benign tissues." (PMID 28537908, 2017). "The breadth of responses includes anti-tumor effector (Granzyme B, IFN-γ, MIP-1α, TNF-α), stimulatory (GM-CSF, IL-2, IL-8), regulatory (IL-4, IL-13, IL-22), and inflammatory (IL-6, IL-17A) functions." (PMID 29157295, 2017). "To further confirm the anti-inflammatory effects of L-4F, we analyzed mRNA levels of the inflammatory cytokines IL-17A, IFN-γ, IL-6, and IL-1β in tumor tissues from Sc-4F- or L-4F-treated tumor-bearing mice." (PMID 29245934, 2017). "In the present study, serum IL-17A was high in the BCG and MMC groups, both of which displayed anti-tumor activity." (PMID 28406993, 2017). "More importantly, treatment with combined anti-IL-17A and anti-PDL1 antibodies enhanced antitumor effects in favor of tumor eradication." (PMID 27935862, 2017). "We further analyzed the percentages of IL-17A-, IL-6-, IFN-γ-, IL-4- and GM-CSF-producing Th cells (T helper cells) in tumor-infiltrating lymphocytes (TILs) from H7 tumor-bearing mice treated with Sc-4F or L-4F." (PMID 29245934, 2017). "Relative expression of interleukin (IL)-17A was lower, whereas that of interferon (IFN)-γ was higher in tumor tissues than in benign tissues." (PMID 28537908, 2017). "We established a murine tumor model by s.c. injection of EO771 cells and treated the mice with anti-IL-17A Ab to study the roles of IL-17A in tumor-bearing mice in vivo." (PMID 27935862, 2017). "IL-17A and IFN-γ were expressed in the cytoplasm of tumor cells or TILs, FOXP3 was expressed in the nucleus of tumor cells or TILs." (PMID 28537908, 2017). "The present study provided novel evidence of decreased generation of Th17 cells and IL-17A and increased expression of IFN-γ and IRF8 in the DLBCL tumor microenvironment." (PMID 28537908, 2017). "Our findings strongly suggest that IL-17A serves as an inflammatory cytokine to promote PDL1 expression, and targeting of IL-17A and PDL1 enhances tumor-specific immune responses and breaks tolerance to tumor antigens." (PMID 27935862, 2017). "Here, we found that the levels of IL-17A in serum and tumor samples were significantly increased in TSCC patients and positively correlated with tumor metastasis and clinical stage." (PMID 28035060, 2017). "In the murine cancer model, targeting of IL-17A inhibited PDL1 expression in the tumor microenvironment, decreased the percentage of Treg cells in tumor-infiltrating lymphocytes, and promoted CD4+ and CD8+ T cells to secrete interferon gamma." (PMID 27935862, 2017). "For example, IL-17A has been shown to inhibit tumor growth in immune competent mouse models via enhancing the generation of MHC-I and MHC-II antigens and tumor-specific cytotoxic cells." (PMID 28123897, 2016).
tumor (continued). "Mechanistically, IL-17A activates the NF-κB pathway in CRC cells, thereby driving tumor survival and growth [see also tumor necrosis factor (TNF)]." (PMID 27148488, 2016). "Interleukin 17A (IL-17A), a pro-inflammatory cytokine secreted by CD4+ Th17 cells, triggers tumor cells to produce interleukin 6 (IL-6), which in turn activates STAT3-dependent survival and angiogenesis." (PMID 27341128, 2016). "Although both IL-17A and MMP-3 are known to be involved in the initiation and progression of tumor cells, their interaction has yet to be determined." (PMID 26850593, 2016). "Constitutive expression of IL-6, TGF-β1, IL-17A, VEGF, IL-4, IL-10 and IDO by tumor cells as a major component of immune escape and immunosuppression in human EOC." (PMID 27118139, 2016). "We found that anti-IL-17A antibody treatment indeed reduces the CII-induced SDF-1 levels in the bone and lung prior to tumor development." (PMID 24674692, 2014). "IL-17A expression was increased not only in tumors, but also in CD4+ T cells isolated from the tumor draining lymph nodes." (PMID 25181290, 2014). "Inhibition of IL-17A at tumor sites significantly suppressed CD31, MMP9, and VEGF expression in tumor tissue." (PMID 23372655, 2013). "In addition to BCL2A1 expression, we also identified a pre-M2 phenotype in IL-17A-treated DC, opening the view that, in the absence of IFN-γ, IL-17A-dependent myeloid cell plasticity may give rise to M2-like tumor-associated macrophages." (PMID 23441221, 2013). "In contrast, we found high frequencies of IL-17A-producing T (Th17 and Tc17) cells in MB49-I tumours as compared to MB49 ones." (PMID 24142880, 2013). "This is particularly important in the light of a downregulation of NK cells and the immune cells containing interleukin 2, IL-17a (TH17) and IL-21 which suggests the influence of tumor cells on the innate immune system." (PMID 23877403, 2013). "We then detected cytokines IL-1β, IL-6, IL-17A, IL-21, IL-23 or TGF-β by ELISA in sera and supernatants from both normal and tumor tissues cultured ex vivo." (PMID 22994684, 2012). "Hypomethylated genes in the TNF network were cytokines (CCL3, CCL4, CCL7, CCL8, CCL22, IL21, IL17A, EBI3) that can either stimulate or inhibit tumor growth and progression." (PMID 22768131, 2012). "The expression of IL-17A and IL-17A receptor in NSCLC tissue samples in tumor adjacent lung tissue and in L3, L4 and A549 cell lines was tested." (PMID 21949768, 2011). "The presence of the Th17-related cytokine transcripts, IL-17A (IL-17), IL-21 and IL-22 mRNA, and of GFP was analyzed in extracts from the eyes 19 days after inoculation of tumor cells or injection of PBS." (PMID 21949734, 2011). "They found that CR and PR patients had higher levels of GZMB+ MAIT and IFN-γ+ MAIT (anti-tumor MAIT) after treatment compared to SD patients, and CR and PR patients showed a reduction in IL-17A+ MAIT (pro-tumor MAIT) levels post-treatment, while PD and SD patients did not exhibit this difference." (PMID 41535994, 2026). "Other factors, including IL17A, IL1, and TNF(denoted by black arrows), were also activated, whose functions might initiate tumor progression." (PMID 40225855, 2025). "OSCC-derived EVs were shown to promote tumor growth by altering the TME, increasing levels of inflammatory cytokines, including IL-17A, IL-10, IL-1β, and immune checkpoint molecules, including programmed death-ligand 1 (PD-L1), and activating the IL-17A signaling pathway, including TRAF6 and c-FOS." (PMID 40699851, 2025). "Non-canonical CD8+ T-cell subpopulation producing IL-17A (Tc17) accelerates tumor growth via IL-17RA-dependent stroma modification, as IL-17A and TNF synergistically induce differentiation of inflammatory CAFs (iCAFs) by IL-17RA." (PMID 40427098, 2025).